IGFBP3 (insulin like growth factor binding protein 3)
Diseases named in the same sentence as IGFBP3 in open-access papers (continued):
Sharing a sentence is not in itself a finding about the gene and the disease.
cancer (continued). "Role of FOXA1 has been elaborated in many cancers, prostate cancer cell proliferation and cancer progression was mediated through FOXA1 by targeting the tumor suppressor gene IGFBP-3." (PMID 33344262, 2020). "IGFBP-3, known to regulate cell proliferation, was also increased in GBM-MG crosstalk, though its role in cancer progression remains to be fully understood." (PMID 33208156, 2020). "Recently published studies dedicated to other potential urinary protein biomarkers have shown that levels of some of them (EN2, αHGF, IGFBP3, ZAG) are elevated in PCa, while the urinary ANXA3, PAP, and PSA have inverse relationship with cancer." (PMID 33791193, 2020). "In keeping with the importance of IGFBP3 and TM219 in the regulation of cell survival, IGFBP3 has been shown to be dysregulated in a variety of cancers." (PMID 31220095, 2019). "IGF-binding protein-3 (IGFBP-3) is the major carrier protein for IGF-1 and plays a role in cancer, apoptosis, and pathogenesis of ischemia reperfusion after liver injury." (PMID 31057604, 2019). "ΔNp63 and IGFBP‐3 expression are inversely correlated in human SCC samples and decreased IGFBP3 expression is correlated with unfavourable prognosis in human cancers, implying a potential relevance of IGFBP3 suppression in SCC development." (PMID 30845357, 2019). "To understand the physiological relevance of MTA1 stimulation of IGFBP3 expression in cancer, we examined the status of MTA1 and IGFBP3 in context of DNMT3a expression in human tumors." (PMID 28393842, 2017). "Of the genes that overlapped between the P63-containing FAIRE peaks and P63 knockdown in carcinoma-derived cell lines, F3, HBEGF, IGFBP3 and IL1B were further investigated by RT-qPCR in P63 siRNA-treated NHU cells." (PMID 28282036, 2017). "IGFBP-3 is a major IGF-binding protein in humans, and it enhances angiogenic activity in cancer through both IGF-dependent and IGF-independent mechanisms." (PMID 27528036, 2016). "The insulin-like growth factor-binding protein-3 (IGFBP-3) influences several molecular mechanisms or signaling pathways that determine cell death or survival, particularly in the context of cancer." (PMID 27144338, 2016). "The cancer pathway finder PCR array revealed 9 genes, including ACSL4, BIRC3,CA9, CCL2, FLT1, FOXC2, G6PD, IGFBP3 and SNAI2, with significantly altered expression in the siRNA-treated MCF-7 cells." (PMID 27478411, 2016). "IGFBP3 prevented RAR heterodimerization, and modulated retinoic acid-sensitivity in human cancer cells." (PMID 27563882, 2016). "As it binds to IGF which is an activator of IGFIR, a known oncogene in many types of human cancer cells, we investigated IGFIR activation status after IGFBP3 depletion." (PMID 24260413, 2013). "IGFBP3 is another HRG that is highly induced by HIF and it is known to have IGF-dependent and IGF-independent biological functions that are important for cancer development." (PMID 24260413, 2013). "In this study, we evaluated the molecular mechanism of IGFBP-3 regulation in cancer cells and found that methylation at the CpG sites of the IGFBP-3 promoter was significantly correlated with IGFBP-3 silencing in OEC tumors." (PMID 20003326, 2009). "IGFBP-3 is known to regulate TGF-β in cancer cells but has not been widely reported in fibrotic disease." (PMID 41226289, 2025). "At the same time, multiple collagen-related genes (COL6A2, COL3A1, COL4A1, and COL4A2) in the MSC-2 cluster were upregulated in bone metastases, which is consistent with our observation of IGFBP3, TAGLN, LUM, COL6A1, COL6A2, and COL3A1 in pan-cancer in Fig. (1d)." (PMID 39156727, 2024).
cancer (continued). "In this sense, adding the IGFBP-3 protein to the LNCaP cell growth medium inhibited growth through p21/WAF1; IGFBP3 and MAPK/ERK signaling mediates melatonin-induced antitumor activity in PCa; and IGFBP-3 also promotes TGFβ-mediated EMT and cell motility in other human cancer cells." (PMID 38542079, 2024). "Additionally, 43 regulated genes are involved in cancer progression, particularly by modulating the PI3K/AKT pathway and upregulating IGFBP3, a key player in cancer cell apoptosis." (PMID 39407697, 2024). "This may be a key mechanism by which IGFBP3, IGFBP5, and possibly other IGFBPs may regulate the balance between cell death and survival in response to some cancer therapies." (PMID 37088808, 2023). "Furthermore, according to the results from CCLE analysis, IGFBP2, IGFBP3, IGFBP4 and IGFBP6 are highly expressed in most cancer cell lines at the cell level." (PMID 37088808, 2023). "Interestingly, several studies have shown that IGFBP-3, known to regulate cell proliferation, was also increased in GBM-microglia crosstalk, though its role in cancer progression remains to be fully understood." (PMID 35654889, 2023). "Previous studies had demonstrated that the absence of IGFBP3 was involved in intrinsic or acquired resistance to chemotherapy or targeting therapy in different types of cancer." (PMID 36660244, 2023). "Insulin-like growth factor binding protein-3 (IGFBP-3), a major IGFBP species in circulation, has been demonstrated to have not only direct antitumor functions in human cancers but also anti-inflammatory properties in normal cells through the activation of a specific receptor, IGFBP-3R." (PMID 36430216, 2022). "Notably, IGFBP-2, IGFBP-3, and IGFBP-5 participate in a wide variety of ncRNA-regulated pathways, with both stimulatory and inhibitory effects on cancer cell functions." (PMID 35597813, 2022). "Furthermore, cancer tissues with methylated HOXD10 revealed low expressions of both miR-7 and IGFBP3 (p < 0.01)." (PMID 34790580, 2021). "These promising findings in other cancers, together with our findings in the present study, lead us to suggest that the potential role of TM4SF1 and IGFBP3 as predictive biomarkers of response to vinflunine treatment in aUCC merits further study in a larger cohort of patients." (PMID 34944855, 2021). "More importantly, increased expression of the IGFBP3 mRNA and protein in ccRCC has been described in some clinical investigations, while kidney specimens without cancer show little or no expression of this molecule 11,17." (PMID 34512163, 2021). "Since the IGF axis could contribute to cancer progression and invasion, it is now widely accepted that aberrant methylation of IGFBP7, IGFBP-4, IGFBP-3, IGF-1R, IGF-1, and IGF-II promoters could be a potential factor in various common human cancers." (PMID 33768092, 2021). "Growth factor sequestration by IGFBP-3-Fc enhances the activity of EGFR inhibitors by decreasing cell survival and inhibiting bFGF, HGF, and IGF1 growth factor rescue and also potentiates the activity of other cancer drugs." (PMID 32066763, 2020). "The expression of IGFBP3 and IGFBP7 is often reduced in several kinds of cancers." (PMID 32500027, 2020). "Not surprisingly, the role of IGFBP family members in cancer is controversial: They were proposed as inhibitors, but elevated IGFBP‐3 serum levels predicted increased incidence of CRC and high IGFBP3 gene expression was associated with poor overall survival." (PMID 32767843, 2020). "At present, for the cancer cell, specific pro-apoptotic properties of IGFBP-3 and IGFBP-3R agonistic mAb are not fully elucidated." (PMID 32443727, 2020). "As the majority of circulating IGF-1 is bound to IGFBP-3, the IGF1:BP3 ratio may play a critical role in cancer progression." (PMID 28417914, 2017).
cancer (continued). "Overall, results presented here show that the high levels of IGFBP3, low levels of DNMT3a, and high levels of MTA1 may result in poor prognosis of cancer patients and that the expression of IGFBP3 by MTA1 could be regulated by direct or indirect mechanisms." (PMID 28393842, 2017). "Unlike IGFBP3, which induces antitumor activity in different types of cancers, IGFBP2 promotes tumorigenesis, cancer cell invasion, metastasis, and cancer stem cell expansion." (PMID 28036255, 2017). "To date, however, there is no report, demonstrating an interaction between TPX2 and IGFBP-3 in any cancer cells." (PMID 25914189, 2015). "Collectively our data suggest that PRIMA-1 is not useful in reversing downregulation of IGFBP-3 induced by DNA-damaging agents in order to restore an IGFBP-3-induced apoptotic response of cancer cells to these drugs." (PMID 26378048, 2015). "In summary, we report that the operator's choice of which biopsy to conduct gene expression analysis on does not have any dominant impact on the results of IGFBP3 and F3 gene expression measurements in cancer epithelial cells." (PMID 25296164, 2014). "Along with IGF-1 ligand, IGFBP3 is one of the major regulators of receptor activity in the IGF-IR signaling axis and a major binding protein of IGF-1 ligand that both potentiates and inhibits its interaction with IGF-IR in different cancers." (PMID 24039934, 2013). "Unlike IGFBP3, which induces antitumor activity in different types of cancers, IGFBP2 has been shown to promote tumorigenesis, cancer cell invasion, metastasis, cancer stem cell expansion, and tumor angiogenesis in various types of cancers." (PMID 24069370, 2013). "There is also interplay between IGFBP3 and EGFR in cancer cells." (PMID 24019942, 2013). "Furthermore, IGFBP-3 levels have been inversely associated with prostate carcinogenesis and the negative correlation between IGFBP-3 levels and cancer risk is consistent with a protective role of IGFBP-3, i.e., high IGFBP-3 concentrations may lead to reduced IGF-I bioavailability." (PMID 23519101, 2013). "The insulin-like growth factor binding protein-3 (IGFBP3) is the major binding protein and regulator of IGF-1 ligand bioavailability and has been reported to inhibit as well as potentiate the activity of IGF-IR signaling in different cancers." (PMID 24039934, 2013). "Recent studies documented that IGFBP-3, one of EGFR downstream targets, plays an important role in modulation of radiosensitivity of different human cancers, and EGF could down-regulate IGFBP-3 expression in esophageal squamous carcinoma cells." (PMID 23232108, 2012). "Interestingly, in undifferentiated cells, genes involved in cancer/inflammatory pathways such as CXCL12, IGFBP3, IL1B, and WNT5A were down-regulated by PCB-153, whereas they were up-regulated by AhR ligands." (PMID 22262711, 2012). "After adjustment for other factors, preoperative serum total IGF-1 or IGFBP-3 levels failed to predict cancer death and recurrence." (PMID 18781172, 2008). "A recent study found that in vitro, IGFBP-3 enhanced TRAIL induced apoptosis in cancer cells but did not have a similar effect on non cancer cells." (PMID 18498652, 2008). "In the adjacent normal tissues, however, IGFBP3 expression levels were somewhat higher in patients with cancer than in patients with BBD, although the difference was not statistically significant." (PMID 17210081, 2007). "We therefore are confident that the general conclusion that none of the growth factors measured (IGF1, IGF2 or IGFBP3) have any value in cancer screening can be extended to all the main cancers in men and women." (PMID 16804529, 2006).
cancer (continued). "Our results show that none of the growth factors measured (IGF1, IGF2 or IGFBP3) have any value in cancer screening in men." (PMID 16804529, 2006). "As reported recently, we have also observed the reduced expression of IGFBP-3 in several tumors such as, breast (9/41), uterus (11/42), ovary (6/16), kidney (6/20), and prostate (1/4) using the cancer profiling array (BD bioscience, data not shown)." (PMID 15661074, 2005). "The patterns of risk association between circulating levels of insulin-like growth factor (IGF)-I, and its main binding protein, IGFBP-3, differ between smoking and nonsmoking-related cancers." (PMID 15354219, 2004). "This parallel increase in IGF2 transcription, coupled with defective cancer processing, generates the known high-molecular IGF-II pro-hormone variants, which are refractive to IGFBP-3 (and SpI2-6/IGF2R) binding but not to the IGF-II RTKs (IGF-IR and IRA) which are efficiently activated." (PMID 38255147, 2023). "Independent of IGFs, IGFBP-3 could regulate cell proliferation and apoptosis, leading to the carcinogenesis of certain common cancers." (PMID 35237523, 2022). "Importantly, IGFBP-3R (TMEM219) agonists, in particular TMEM219 agonistic mAbs, are very attractive cancer therapeutics since these agonists would exhibit no other biological activities of IGFBP-3 induced by the interaction with other binding partners." (PMID 32443727, 2020). "Moreover, IGFBP3 was up-regulated by HMOX1, which attenuated migration capability of cancer cells." (PMID 31527696, 2019). "IGFBP-3-mediated actions in cancer vary in a disease-specific manner and some studies suggest that intracellular IGFBP-3 functions may be independent of its IGF binding ability." (PMID 30833285, 2019). "Neither normal nor cancer (SqCC/Y1) exosomes had any significant effects on IGFBP3 gene expression." (PMID 30008265, 2018). "Despite extensive investigation showing the involvement of IGFBP-3 in cancers, it is not a currently used cancer biomarker because it is debatable whether IGFBP-3 is up- or down-regulated in cancers." (PMID 27144338, 2016). "Furthermore, IGFBP-3 below 10 μg/mL failed to restrain ATP production, which is indicative of cancer cell proliferation, and to change the growth rate of Capan-1 cells (at all concentrations tested)." (PMID 26975989, 2016). "Taking these findings together, IGFBP-3 has been suggested to be a key mediator of radiation-induced apoptosis that could act as a radiosensitizer in ESCC, facilitating the development of individualized cancer management." (PMID 26670461, 2015). "Our data suggested that neutralizing IGFBP-3 activity did not affect cancer cell colony formation promoted by NAFs, indicating that IGFBP-3 may not be the contributing factor in this soft agar assay system." (PMID 21249190, 2011). "Given IGFBP3's putative role as a negative regulator of IGF1 signalling, its anti-proliferative role and the negative correlation between serum IGFBP3 levels and cancer risk, we investigated a possible link between its expression and IGF1 signalling." (PMID 20840765, 2010). "Thus, we investigated the effect of mild aerobic exercise training at LT level on the circulating levels of IGF-I, IGFBP-1, and IGFBP-3 to determine an optimal exercise intervention that can induce favorable changes in IGF-I and IGFBP-1 levels for cancer prevention in healthy men." (PMID 20885914, 2010). "For some treatment regimens, statistical significance was seen in IGF-I, IGFBP-3 and PAPP-A between the cancer and non-cancer individuals, but biological relevance was reported as low." (PMID 38395880, 2024). "Serum glucose, HbA1c, IGF-1, IGFBP3 and HOMA were not independently related to long-term cancer mortality." (PMID 23405181, 2013). "Tumors with IGF1R-positive and IGFBP3-negative expression (n = 32) were significantly frequently found to have Stage II and III cancer (χ2 test, p = 0.011) compared to the other groups (n = 90)." (PMID 23962053, 2013).
cancer (continued). "No IGFBP-3 was secreted by any culture but 24-kDa IGFBP-4 was found in 3 out of 10 normal and 5 out of 10 cancer tissues." (PMID 9218734, 1997). "However, data on the interplay between cancer cells and the TME with regard to IGFBP3-regulated cisplatin efficacy are currently lacking." (PMID 38169528, 2024). "This suggests a previously unrecognized involvement of IGFBP-3 in chemotherapy-induced DNA DSB repair, which may in some circumstances lead to cancer cell recovery rather than apoptosis in response to cytotoxic drugs." (PMID 26221601, 2015).
infection (14 papers, 2009 to 2025). The state of being infected such as from the introduction of a foreign agent such as serum, vaccine, antigenic substance or organism. "Age, sequential organ failure assessment (SOFA) score, multiple sources of infection, and IGFBP-3 levels independently predicted 1-year mortality." (PMID 40724799, 2025). "There was an increase in MAST4, FABP1, and KLKB1 levels that lasted until 18 h after LASV infection, whereas increased concentrations of IGFBP3 lasted until 48 h after infection." (PMID 35337059, 2022). "On the contrary, cells treated with TNF-α and insulin together showed more than a 50 percent decrease in glucose uptake but infection with IGFBP-3 abolished the TNF-α effect and restored levels of glucose uptake." (PMID 23383064, 2013). "TNF-α inhibits IRS-1, GLUT4 and adiponectin in TNF-α-treated control cells, however, infection with Ad:IGFBP-3 restored IRS-1, GLUT4 and adiponectin mRNA and protein levels." (PMID 23383064, 2013). "Increase in the mRNA levels of ICAM-1, VCAM-1 and MCP-1 was observed on addition of CRP or high glucose and infection with IGFBP-3 significantly decreased these levels." (PMID 23383064, 2013). "However, in the present study, forced expression of IGFBP-3 by infection with an adenoviral vector or addition of recombinant IGFBP-3 only slightly increased the growth-inhibitory and apoptotic effects of EGFR-TKIs." (PMID 24339922, 2013). "On infection with Ad:EV, Ad:IGFBP-3 and Ad:IGFBP-3GGG mutant, semi-quantitative PCR shows that the effect of Ad:IGFBP-3GGG on the mRNA levels of GLUT4, IRS-1, adiponectin and MCP-1 was similar to Ad:IGFBP-3 suggesting that IGFBP-3 effect on the NF-κB pathway in adipocytes was IGF-independent." (PMID 23383064, 2013). "Ad-IGFBP3 infection alone was cytotoxic relative to Ad-EV at 25 moi (p = 0.0024)." (PMID 19903356, 2009). "Parasitic infection of colitic mice resulted in upregulation of mucosal AREG, EGF, FGF-2, and IGFBP-3 in the intestine of the host and better adaptation (infectivity)." (PMID 36836678, 2023). "On the contrary, MOPV infection led to the late (48 h) release of PSMD2, RPS11, HNRNPA3, ATP1A1, TARS1, and PRKAR1A, whereas significantly elevated levels of IGFBP3 were found at both timepoints." (PMID 35337059, 2022). "Since the somatrotropic axis plays an important regulatory role during host immune-inflammatory responses to infection, we then investigated circulating IGF-I and IGFBP-3 levels in the context of ENL episodes." (PMID 22166091, 2011). "Infection and inflammation were linked to evidence of GH resistance, whereas levels of GH, IGF-1, and IGFBP-3 were associated with growth indices independent of hsCRP." (PMID 27712965, 2017). "Furthermore, credible evidence has shown that, during the immune-inflammatory response to infection, the GH/IGF-I/IGFBP-3 somatotropic axis exercises a prominent regulatory role." (PMID 22166091, 2011). "Infection with an adenoviral vector expressing IGFBP3 (Ad-IGFBP3) but not empty vector (Ad-EV) resulted in high, sustainable levels of IGFBP3." (PMID 19903356, 2009).